CRP (C-reactive protein)
Diseases named in the same sentence as CRP in open-access papers (continued):
Sharing a sentence is not in itself a finding about the gene and the disease.
gastric cancer (continued). "The significance of the C-reactive protein-albumin-lymphocyte index [CALLY index (CI)] as a prognostic factor in gastric cancer remains unexplored." (PMID 40144575, 2025). "The combined use of arginine and glutamine in enteral and parenteral nutrition for patients after gastric cancer surgery has led to increased levels of albumin, serum protein, and transferrin, as well as decreased levels of C-reactive protein, C3, and C4." (PMID 39897929, 2025). "The PPS, a combination of prealbumin and CRP, can identify a wider range of patients with poor OS than the mGPS or prealbumin alone in patients with gastric cancer after gastrectomy." (PMID 39594844, 2024). "CRP is a highly sensitive marker for inflammation and serves as a prognostic indicator in various primary malignancies, including gastric cancer." (PMID 39553069, 2024). "In many studies evaluating patients with advanced gastric cancer who underwent surgery, it has been emphasized that the CRP/albumin level is an important factor in predicting prognosis and mortality." (PMID 38792528, 2024). "CRP value and derivates have been found to have a predictive role in several diseases and procedures, including major abdominal surgery, gastric cancer, renal transplantation, and COVID-19 infection." (PMID 39685924, 2024). "In contrast, CRP-spike was associated with lower PS and NLR in the gastric cancer cohort and higher haemoglobin and albumin in the oesophageal cancer cohort." (PMID 39516365, 2023). "The C-reactive protein-to-serum albumin ratio (CAR) is an inflammation-based prognostic marker in gastric cancer." (PMID 37373912, 2023). "As a simple and cheap inflammatory indicator, postoperative CRP/Alb ratio is an independent predictor of the prognosis of early and locally advanced gastric cancer." (PMID 37735699, 2023). "The following variables were analyzed: age, sex, stage of gastric cancer, CRP, oral hygiene, oral dryness, tongue pressure, occlusal force, tongue and lip movement function, masticatory function, and swallowing function." (PMID 37262024, 2023). "As for the relationship between preoperative CRP/Alb ratio and long-term survival of patients with gastric cancer, we reached a conclusion consistent with previous studies." (PMID 37735699, 2023). "The ORR of nivolumab monotherapy was reported to be 11.2% in gastric cancer and 17.2% in oesophageal cancer, which corresponds to 11.8% and 18.3% of patients characterised as CRP-spike in this study." (PMID 39516365, 2023). "The role of postoperative of the ratio of c-reactive protein to albumin (CRP/Alb ratio) in the prognosis of gastric cancer is rarely evaluated." (PMID 37735699, 2023). "Several studies have shown that circulating levels of CRP were increased in patients with different types of cancer, such as lung, liver, breast, pancreatic, ovarian, and stomach cancer." (PMID 37373957, 2023). "Although studies have reported the prognostic value of these indicators, this is the first study to estimate the postoperative inflammatory indices level, especially CRP/Alb ratio on OS for early and locally advanced gastric cancer." (PMID 37735699, 2023). "Our purpose was to investigate the correlation of the postoperative CRP/Alb ratio and long-term prognosis of gastric cancer." (PMID 37735699, 2023). "We assessed the following parameters: body mass index, stage of gastric cancer, C-reactive protein, total lymphocyte count, albumin, and prognostic nutritional index." (PMID 37262024, 2023). "The present study showed that CRP-increase is associated with higher PS, LDH, and NLR and lower haemoglobin and albumin in the gastric cancer cohort, and higher NLR and lower haemoglobin and albumin in the oesophageal cancer cohort." (PMID 39516365, 2023). "According to a clinical study on body composition and surgical outcomes for gastric cancer, VAT was associated with a higher postoperative level of serum C-reactive protein (CRP) and more postoperative complications." (PMID 37653410, 2023).
gastric cancer (continued). "In this study, using Kaplan–Meier to assess, and the results were consistent with previous studies: preoperative high CRP level or low albumin level were both indicators of poor prognosis in patients with gastric cancer." (PMID 37735699, 2023). "There are several data proposing CRP (mean approx. > 80 mg/L) as a marker for diagnosis and prognosis in stomach cancer/gastric carcinoma patients, and that it can independently predict short-term survival for stage IV gastric cancer patients." (PMID 37873776, 2023). "In the gastric cancer cohort, the CRP-spike, CRP-flat, and CRP-increase subgroups included 9, 37 and 30 patients, respectively." (PMID 39516365, 2023). "In multivariate analysis, low CRP/Alb ratio predicted long DFS of gastric cancer patients (HR 1.42, 95% CI 1.08–1.87, P = 0.012)." (PMID 37735699, 2023). "Presepsin levels on PODs 3, 5, and 7 after gastrectomy for gastric cancer are valuable biomarkers for detecting postoperative infectious complications, compared with other inflammatory biomarkers such as CRP, WBCs, and Neuts." (PMID 36494434, 2022). "As a promising marker, LCR has demonstrated higher ability in predicting cancer surgery and oncological outcomes in gastric cancer, rectal cancer, and cholangiocarcinoma compared to NLR, CRP, nutritional risk index (NRI), PLR, PI, PNI, GPS, and mGPS." (PMID 36266627, 2022). "A meta-analysis of gastric cancer showed that the C-reactive protein (CRP) level is significantly declined in patients applying ERAS after 3/4 and 7 days of surgery." (PMID 35844438, 2022). "The purpose of this study was to investigate the effect of CRP/Alb ratios on prognosis in gastric cancers." (PMID 35547460, 2022). "This study focused on assessing the role of the Peking prognostic score (PPS), a novel prognostic index based on muscle atrophy and lymphocyte-to-C-reactive protein ratio, within gastric cancer patient prognosis." (PMID 35747263, 2022). "This study aimed to evaluate the usefulness of presepsin for determining infectious complications after gastrectomy for gastric cancer, compared with CRP, WBCs, and Neuts." (PMID 36494434, 2022). "In the univariate analysis, macroscopic type of gastric carcinoma, histological classification, site of metastasis (liver, bone, or peritoneum), history of gastrectomy, NLR, Glasgow prognostic score, and CRP were significantly associated with the OS." (PMID 34845844, 2022). "Dexmedetomidine suppressed the rapid increase of cytokine, TNF-α, and IL-6 levels in gastric cancer patients and decreased IL-6 and CRP levels and the inhibition of T-lymphocyte subsets in colon cancer patients undergoing radical surgery." (PMID 34300310, 2021). "More impressively, adjuvant chemotherapy seems to only improve the prognosis for stage II/III gastric cancer with pre‐CRP ≥3.1 mg/L and post‐CRPmax ≥77.1 mg/L." (PMID 33270989, 2021). "To further evaluate the predictive value of pre‐CRP and post‐CRP for the prognosis of gastric cancer (GC), we constructed a predictive model, model A, including pre‐CRP, post‐CRPmax, and pTNM stage." (PMID 33270989, 2021). "The platelet-to-lymphocyte ratio (PLR) and C-reactive protein (CRP), which are two inflammation-related biomarkers, have been confirmed to be prognostic indicators in early gastric cancer, gastrointestinal cancers, and CRC." (PMID 34001040, 2021). "Using randomized phase III trial data, we found that both high pre‐CRP and high post‐CRPmax statuses were clinically actionable as potential prognostic indicators in gastric cancer." (PMID 33270989, 2021). "Shishido et al13 reported that CRP on postoperative day (POD) 3 predicted infectious complications following gastric cancer resection." (PMID 32724882, 2020). "We examined the effect of factors that had been reported to be useful for predicting infectious complications after gastric cancer surgery on CRP levels on POD3." (PMID 32724882, 2020).
gastric cancer (continued). "Our results demonstrate that acupuncture and moxibustion contributes to inhibiting progression and improving prognosis of advanced gastric cancer by reversing Th1/Th2 shift and downregulating IL-6, CRP, and Ca199." (PMID 33144870, 2020). "Altogether, our results showed that acupuncture and moxibustion can inhibit gastric cancer development by promoting Th1 dominance and decreasing tumor marker Ca199 and proinflammatory factors IL-6 and CRP." (PMID 33144870, 2020). "The aim of this retrospective study was to investigate the elevation rate of CRP as an early predictor of postoperative complications after LG for gastric cancer." (PMID 31429742, 2019). "In minimally invasive surgery and laparotomy for colorectal and gastric cancer, postoperative CRP levels have been observed to be significantly lower after minimally invasive surgery if no complications arise." (PMID 31429742, 2019). "Some researchers have reported that CRP is an independent predictor of prognosis in gastric cancer patients." (PMID 31116313, 2019). "The purpose of this study was to evaluate the prognostic value of C-reactive protein/albumin ratio in patients with gastric cancer." (PMID 29065877, 2017). "Recently, the prognostic ability of CRP/Alb has been reported in patients with hepatocellular carcinoma, gastric cancer and esophageal squamous cell carcinoma." (PMID 28431566, 2017). "Many recent studies have shown that the levels of systemic inflammatory markers such as C-reactive protein, albumin, fibrinogen, and circulating cellular components are useful prognostic markers for gastric cancer." (PMID 26075713, 2015). "It has been suggested that NLR (calculated as neutrophil count divided by lymphocyte count), CRP level, and albumin level reflect host-response factors in various solid tumors including gastric cancer." (PMID 24906485, 2014). "All patients with gastric cancer whose concentration of C-reactive protein value exceeded 10 mg/L were qualified for the study." (PMID 23554823, 2013). "CRP, IL-6, and IL-23 were the markers used in the assessment of inflammation in patients with gastric cancer." (PMID 23554823, 2013). "In the logistic regression analysis, ADN ratio was still significant even when both CRP levels and ADN ratio were included in Model 4, indicating that ADN ratio was an independent risk factor of postoperative infection following gastric cancer surgery." (PMID 23520452, 2013). "In our study of patients with gastric cancer, inflammation was observed which was subsequently confirmed by the results of determinations of C-reactive protein and IL-6." (PMID 23554823, 2013). "The negative response to IVC treatment with dosages 15 g-50 g was found in patients with gastric cancer (CRP was increased from 1.0 mg/L to 60 mg/L in 160 days, 15 IVC treatments)." (PMID 22963460, 2012). "We then employed apoB-100-normalized apoC-I and apoC-III, CA19-9 and CRP levels to generate rules set for stomach cancer prediction." (PMID 21267442, 2011). "Our results also demonstrated that increased CRP was associated with shorter PFS, and a GPS ≥ 1 was associated with shorter OS in advanced gastric cancer in palliative chemotherapy settings." (PMID 22103888, 2011). "In gastric cancers, almost all studies evaluated the prognostic value of the preoperative CRP in resettable tumors." (PMID 22103888, 2011). "In a recent study of 204 patients who underwent curative resection of gastric carcinoma, preoperative CRP elevations were found to be independently predictive of shorter overall survival." (PMID 22103888, 2011). "The principal objective of this study was to determine the relationship between serum IL-6 and CRP levels and malignant tendencies and prognosis in gastric cancer patients." (PMID 19457231, 2009). "The principal objective of this study was to determine the preoperative serum levels of IL-6 and CRP in gastric carcinoma, and to correlate them with disease status and prognosis." (PMID 19457231, 2009).
gastric cancer (continued). "In stomach cancer pre-operative levels of CRP can help in the identification of the patients with a resectable tumour; the pre-operative biochemical measurements do not give any further information on prognosis once stage and site are taken into account." (PMID 6688531, 1983). "Patients with gastric cancer often exhibit elevated serum CRP levels." (PMID 40144575, 2025). "High serum CRP levels negatively affect prognosis, and a nutritional assessment index based on serum CRP levels has been correlated with postoperative complications and long-term prognosis in patients with gastric cancer." (PMID 40144575, 2025). "Therefore, we believe that IBI combined with CRP, neutrophils and lymphocytes can better predict the efficacy of neoadjuvant immunotherapy for advanced gastric cancer than other inflammatory indices." (PMID 39906738, 2024). "According to the results of this study, CEA/albumin and CRP/Albumin ratios may be important in predicting pathological response in patients with locally advanced gastric cancer receiving neoadjuvant therapy and surgery." (PMID 38792528, 2024). "Moreover, we focused on the relationship between postoperative CRP/Alb ratio and prognosis of gastric cancer, which has rarely been reported." (PMID 37735699, 2023). "Postoperative inflammatory factors in patients with gastric cancer should be pay attention, especially postoperative CRP/Alb ratio may be an independent predictor of long-term prognosis of gastric cancer." (PMID 37735699, 2023). "We also investigated whether preoperative CRP/Alb ratio is an independent predictor of DFS in patients with gastric cancer." (PMID 37735699, 2023). "However, the role of postoperative of CRP/Alb ratio in the prognosis of gastric cancer is rarely evaluated." (PMID 37735699, 2023). "In particular, whether postoperative CRP/Alb ratio can predict the long-term prognosis of gastric cancer." (PMID 37735699, 2023). "Meanwhile, we also analyzed the relationship between postoperative CRP or albumin and the long-term survival of patients with gastric cancer, and we also found that patients with high postoperative CRP level or low postoperative albumin level had shorter survival." (PMID 37735699, 2023). "Eventually, we found that postoperative CRP/Alb ratio could act as an independent prognostic marker in early and locally advanced gastric cancer." (PMID 37735699, 2023). "High postoperative CRP levels are related to poor prognosis of gastric cancer." (PMID 36494434, 2022). "A meta-analysis showed that ω-3 PUFAs could improve the nutritional status of patients after gastrectomy of gastric cancer and downregulate the levels of inflammatory indicators, such as C-reactive protein (CRP) and interleukin 6 (IL-6)." (PMID 35910071, 2022). "Furthermore, he demonstrated that preoperative lymphocyte-to-CRP score was an independent prognostic factor for both overall survival and disease-free survival in gastric cancer patients." (PMID 33507925, 2021). "Data from the EPIC study showed that an MD pattern is associated with a 33% reduced risk of gastric cancer, and data from the MOLI-SANI study found a lower level of circulating markers of inflammation such as C-reactive protein (CRP), leukocytes, platelet counts, and granulocyte/lymphocyte ratio." (PMID 30934960, 2019). "In this study, we found that CRP could contribute to predict the stage of gastric cancer and built an exact discriminant formula including CRP to predict the stage." (PMID 29967637, 2018). "Recently, a few studies began studying the predictive value of CRP for gastric cancer resection." (PMID 29065877, 2017). "Shishido and colleagues evaluated that postoperative CRP on POD 3 could predict infectious complications after gastric cancer resection." (PMID 29065877, 2017). "First, these SIRMs like the high CRP level, could reflect progressive nutritional and functional decline of gastric cancer patients." (PMID 27121054, 2016).
gastric cancer (continued). "Additionally, we previously demonstrated in a large-scale multicenter study that the postoperative C-reactive protein (CRP) level was a better predictor of prognosis in patients with gastric cancer than the occurrence of intra-abdominal infectious complications." (PMID 40638018, 2025). "In this respect, we should mention the fact that the studies published so far have demonstrated that the CRP/albumin ratio represents an important parameter in order to predict the long-term outcomes in other malignancies, such as hepatocellular carcinoma, esophageal or gastric carcinoma." (PMID 39061143, 2024). "CRP, a substance produced by the body in response to acute regulation of inflammatory cytokines in stress, is one of the most commonly used serum markers to assess the inflammatory status of patients and is identified as a prognostic indicator for patients with gastric cancer." (PMID 35198443, 2022). "Considering the importance of immunity in controlling tumor progression, we studied whether acupuncture and moxibustion can decrease gastric cancer marker Ca199 and proinflammatory factors IL-6 and CRP, which were intimately related with development of gastric cancer." (PMID 33144870, 2020). "In the context of ovarian cancer, AUC analysis has shown that CRP/Alb was superior to other inflammation-based prognostic scores in terms of predictive accuracy, which is consistent with several previous studies in hepatocellular carcinoma, gastric cancer and esophageal squamous cell carcinoma." (PMID 28431566, 2017). "We then employed Clementine 10.0 software on the RNTech samples to assess whether rules set based on apoB-100-normalized C-I and C-III, CA19-9 and CRP serum levels can be used to classify between sera of control and stomach cancer groups of RNTech source as a training source." (PMID 21267442, 2011). "Similar findings have been reported in gastric cancer, where combined analysis of pre-and postoperative LCR (lymphocyte-to-CRP ratio) demonstrated superior prognostic ability compared with either measurement alone." (PMID 41228216, 2025). "To further promote the development of enhanced recovery after surgery (ERAS) in laparoscopic gastric cancer (LGC) surgery, we evaluated and compared the predictive values of CRP, PCT, and IL-6 for infectious complications following LGC surgery." (PMID 38504206, 2024). "In our present study, we investigated the relationship between pathological response and the CRP/albumin and CEA/albumin ratios in patients receiving neoadjuvant therapy for gastric cancer." (PMID 38792528, 2024). "Several inflammation markers have been used to assess the prognosis of gastric cancer, including mGPS, PLR, CRP/Albumin, and HALP." (PMID 38792528, 2024). "In this study, the importance of CRP/albumin ratio and CEA/albumin ratio in the prediction of neoadjuvant treatment response in gastric cancer patients was evaluated." (PMID 38792528, 2024). "The combination of platelet counts and neutrophil to lymphocyte ratio (COP-NLR) in gastric carcinoma, and PI based on WBC and CRP levels in non-small cell lung carcinoma (NSCLC) are used as inflammatory markers." (PMID 39158760, 2024). "Research suggests that the early introduction of EIN after surgery curtails CRP and TNF-αsynthesis, markedly enhancing immune responsiveness and suppressing inflammation in patients with gastric cancer." (PMID 37960219, 2023). "Elevated levels of inflammatory markers, including interleukin-1 beta (IL-1β), C-reactive protein (CRP), and tumor necrosis factor-alpha (TNF-β), have been identified in CP and gastric cancer." (PMID 37568790, 2023). "Mean platelet volume (MPV) was analyzed statistically to find a prognostic relationship between monocyte/lymphocyte ratio, platelet distribution volume (PDW), MPV/platelet, c-reactive protein/albumin ratio (CAR), and gastric cancer." (PMID 35547460, 2022).